SP9 (Sp9 transcription factor)
Description:
Transcription factor which plays a key role in limb development. Positively regulates FGF8 expression in the apical ectodermal ridge (AER) and contributes to limb outgrowth in embryos (By similarity).
Synonyms: ZNF990
Tractability: No criterion of Open Targets' tractability assessment is met for any kind of drug.
Gene: Protein-coding gene on chromosome 2 (174,334,954 to 174,338,500, forward strand). Ensembl gene ENSG00000217236.
Subcellular location: Nucleus
Subcellular location (Human Protein Atlas): Mitochondria
Gene Ontology:
Molecular function: sequence-specific double-stranded DNA binding; DNA-binding transcription factor activity, RNA polymerase II-specific; RNA polymerase II cis-regulatory region sequence-specific DNA binding; sequence-specific DNA binding
Biological process: regulation of transcription by RNA polymerase II; embryonic limb morphogenesis
Cellular component: chromatin; nucleus
Genetic constraint (gnomAD): Loss-of-function variants: 5 observed, 14.39 expected, observed/expected ratio (o/e) 0.35, 90% interval 0.18 to 0.73. The synonymous counts are far from expectation, so gnomAD's model fits this gene poorly and the ratio says little. Missense variants: 542 observed, 571.74 expected, observed/expected ratio (o/e) 0.95, 90% interval 0.88 to 1.02. Synonymous variants: 360 observed, 281.69 expected, observed/expected ratio (o/e) 1.28, 90% interval 1.17 to 1.39.
Homologues: Orthologues: macaque SP9 (99% identical), pig SP9 (99% identical), dog SP9 (99% identical), mouse Sp9 (99% identical), rat Sp9 (99% identical), chimpanzee SP9 (99% identical), guinea pig SP9 (76% identical), zebrafish sp9 (75% identical), tropical clawed frog sp9 (74% identical), Drosophila melanogaster luna (13% identical). Paralogues in human: SP8 (61% identical), SP7 (38% identical), SP6 (30% identical), SP5 (28% identical), KLF11 (21% identical), KLF10 (18% identical), KLF5 (18% identical), KLF13 (17% identical), KLF2 (17% identical), KLF14 (16% identical), KLF4 (16% identical), KLF15 (16% identical), and 10 more.
Diseases named in the same sentence as SP9 in open-access papers:
SP9 is named in the same sentence as 10 diseases in open-access papers, as found by Europe PMC text mining. Sharing a sentence is not in itself a finding about the gene and the disease. The quoted sentences say what the papers report.
Anosmia (1 paper, 2022). An inability to perceive odors. "We have identified a gene regulatory network, Gsx1/2 – Dlx1/2/5/6 – GAD2/1/Sp8/Sp9 – Tshz1 – Prokr2, which governs OBiN development; mutations of some of these genes result in human Kallmann syndrome with abnormal olfactory function (anosmia or hyposmia)." (PMID 34374948, 2022).
breast carcinoma (1 paper, 2023). "Additionally, Tat-SP9 also showed more potent anti-proliferative efficacy than Tat-SP4 in ERBB2-POSITIVE breast cancer cells." (PMID 37958451, 2023).
hepatoma (1 paper, 2024). "One limitation of our study is that transfection of plasmid was used to express Sp9 in hepatoma cells which may not accurately reflect native expression of spliced RNAs and their putative novel proteins." (PMID 38501924, 2024).
nematode infections (1 paper, 2017). "SP9 and Halobacillus alkaliphilus SP22 could produce the compound hexahydro-3-(2-methylpropyl)pyrrolo[1,2a]pyrazine-1,4-dione which is commonly used as a broad spectrum antibiotic for treating some bacterial, fungal and nematode infections." (PMID 28425950, 2017).
cancer (2 papers, 2015 to 2022). A tumor composed of atypical neoplastic, often pleomorphic cells that invade other tissues. "DNA methylation alterations in UNC13A, SP9, GP5, C1QL3, SP8, and VWC2 have not been previously reported in cancer." (PMID 26380585, 2015).
SP9 also shares sentences with these, for which no sentence is quoted: chronic hepatitis B (1 paper); infection (1); Kallmann syndrome (1); polycystic kidney disease (1); tumor (1).